DMD (dystrophin)
Diseases named in the same sentence as DMD in open-access papers (continued):
Sharing a sentence is not in itself a finding about the gene and the disease.
Duchenne muscular dystrophy (continued). "For instance, in Duchenne muscular dystrophy (DMD), compensatory regeneration at earlier stages of disease tends to counter the degeneration of dystrophin-deficient myofibers." (PMID 26203859, 2015). "Duchenne muscular dystrophy (DMD), the most common form of muscular dystrophy, is characterized by muscular wasting caused by dystrophin deficiency that ultimately ends in force reduction and premature death." (PMID 25861640, 2015). "Utrophin upregulation could therefore be a therapeutic strategy in Duchenne Muscular Dystrophy (DMD) that arises from mutation in dystrophin gene." (PMID 26230628, 2015). "Duchenne muscular dystrophy (DMD) is the most common, X-linked, recessive disorder, resulting from genetic deficiency of dystrophin in myocytes." (PMID 26205050, 2015). "Evidence for this comes from a Duchenne muscular dystrophy (DMD) monkey model, in which three different mutations in the dystrophin gene cause the loss of dystrophin in monkey muscle and muscle atrophy, as seen in DMD patients." (PMID 26238861, 2015). "Duchenne muscular dystrophy (DMD) is the most common muscular dystrophy, due to mutations of the X‐linked dystrophin gene." (PMID 26543057, 2015). "Systemic delivery of anti-sense oligonucleotides to Duchenne muscular dystrophy (DMD) patients to induce de novo dystrophin protein expression in muscle (exon skipping) is a promising therapy." (PMID 26634117, 2015). "Duchenne muscular dystrophy caused by variants in the X-chromosomal DMD gene and a complete loss of function of dystrophin is the textbook representative for these entities." (PMID 26438297, 2015). "Duchenne muscular dystrophy (DMD; MIM number 310200) and Becker muscular dystrophy (BMD; MIM number 300376) are allelic dystrophinopathies caused by mutations in the dystrophin gene (MIM number 300377)." (PMID 25852218, 2015). "In particular, Duchenne Muscular Dystrophy (DMD) is a lethal muscle degenerative disease that affects 1 in 3500 males and is caused by mutations in the cytoskeletal protein dystrophin." (PMID 25689854, 2015). "The most prevalent and severe disease is Duchenne muscular dystrophy (DMD), an X-linked disorder caused by mutations in the dystrophin gene, with a world-wide incidence of 1/5000 male newborns." (PMID 26060189, 2015). "We therefore examined ITGB6 expression in the muscles of the Dystrophin mutant mdx mouse, a genetic model of Duchenne Muscular Dystrophy." (PMID 24488487, 2014). "The progressive muscle-wasting disorder Duchenne muscular dystrophy (DMD) is caused by loss-of-function mutations in the DMD gene, which encodes the dystrophin protein." (PMID 24586621, 2014). "Duchenne muscular dystrophy (DMD) is characterized by the absence or reduced levels of dystrophin expression on the inner surface of the sarcolemmal membrane of muscle fibers." (PMID 25244123, 2014). "In Duchenne muscular dystrophy (DMD), the most severe form of these diseases, the mutations in the dystrophin gene lead to muscle weakness and wasting, exhaustion of muscular regenerative capacity, and chronic local inflammation leading to substitution of myofibers by connective and adipose tissue." (PMID 25104934, 2014). "In human muscle, fibrosis is most readily associated with the severe muscle wasting disorder Duchenne muscular dystrophy (DMD), caused by loss of dystrophin gene function." (PMID 24877152, 2014). "Duchenne muscular dystrophy (DMD) is the most common dystrophy affecting approximately 1:4,000 boys, and is caused by mutations in the dystrophin gene." (PMID 24910770, 2014). "Duchenne muscular dystrophy (DMD) is a genetic disease caused by the alteration of geneXp21, which encodes the protein dystrophin." (PMID 25590443, 2014).
Duchenne muscular dystrophy (continued). "A readily available animal model is essential for rapidly identifying effective treatments for Duchenne muscular dystrophy (DMD), a devastating neuromuscular disorder caused by the lack of dystrophin protein, which results from frame-disrupting mutations in the DMD gene." (PMID 25365558, 2014). "The skeletal muscles in Duchenne muscular dystrophy and the mdx mouse model lack functional dystrophin and undergo repeated bouts of necrosis, regeneration, and growth." (PMID 24586653, 2014). "Abnormal expression of the protein dystrophin leads to Duchenne muscular dystrophy, exhibited by a majority of samples in GSE6011; the brain is another major expression site for dystrophin." (PMID 25427176, 2014). "Two decades following the cloning of the dystrophin gene, the gene involved in Duchenne muscular dystrophy (DMD), much effort has been put into finding a cure or therapy that alleviates symptoms." (PMID 24963862, 2014). "The functional replacement of utrophin for dystrophin is one of many attractive therapeutic strategies for the treatment of Duchenne muscular dystrophy." (PMID 23282144, 2013). "Duchenne muscular dystrophy (DMD), the most common monogenic hereditary disease, is caused by defects in the gene encoding dystrophin." (PMID 23732986, 2013). "Duchenne muscular dystrophy (DMD) is a well-known inherited muscular disorder, and the causative gene, Dystrophin, is coded in the X-chromosome." (PMID 24273513, 2013). "Duchenne muscular dystrophy (DMD), an X-linked, recessive disorder, is the most common and severe form of childhood muscular dystrophy, which is caused by mutations in the dystrophin gene." (PMID 23717655, 2013). "The next protein in the study is dystrophin, which is a product of the Duchenne Muscular Dystrophy (DMD) gene." (PMID 24014171, 2013). "Mutations that lead to a complete lack of dystrophin expression tend to cause the more severe Duchenne muscular dystrophy (DMD) phenotype, whereas mutations that lead to an abnormal quality or quantity of dystrophin result in the Becker muscular dystrophy (BMD)." (PMID 23476807, 2013). "Duchenne muscular dystrophy (DMD), a fatal X-linked muscle wasting disorder of childhood, is caused by mutations in the dystrophin gene (DMD), most commonly frame-shifting deletions of one or more exons (for review Emery (2002))." (PMID 24498612, 2013). "Because loss of dystrophin in Duchenne muscular dystrophy (DMD) leads to an almost complete loss of dystroglycan complexes at the myofiber membrane, it is generally assumed that the vast majority of dystroglycan complexes within skeletal muscle fibers interact with dystrophin." (PMID 23951345, 2013). "Dysfunction of dystrophin and SMN are causally related to muscle diseases in that deregulated dystrophin causes Duchenne Muscular Dystrophy whereas Spinal Muscular Atrophy is caused by defective SMN function." (PMID 23727833, 2013). "Utrophin is a protein homologous to dystrophin, the protein missing in Duchenne muscular dystrophy (DMD) patients." (PMID 24295286, 2013). "Prominent muscle regeneration has been observed with MDSPCs transplantation into a dystrophin knockout mouse model of Duchenne muscular dystrophy (mdx)." (PMID 23531345, 2013). "Duchenne muscular dystrophy is due to genetic abnormalities in the dystrophin gene and represents one of the most frequent genetic childhood diseases." (PMID 23828267, 2013). "In this respect, the X-linked muscular dystrophy (mdx) mouse is the most widely used animal model of Duchenne muscular dystrophy for studying secondary effects due to the reduction of the dystrophin-glycoprotein complex." (PMID 23828267, 2013). "Purification of the proteins associated with dystrophin, the gene product responsible for Duchenne muscular dystrophy, led to the discovery of the dystrophin-glycoprotein complex." (PMID 23282144, 2013).
Duchenne muscular dystrophy (continued). "Duchenne muscular dystrophy (DMD) is a fatal neuromuscular disease that affects 1 in 3500 newborn boys and is caused by mutations in the gene encoding dystrophin, a protein that supports muscle fiber strength." (PMID 23846963, 2013). "Stimulating the commitment of implanted dystrophin+ muscle-derived stem cells (MDSCs) into myogenic, as opposed to lipofibrogenic lineages, is a promising therapeutic strategy for Duchenne muscular dystrophy (DMD)." (PMID 23295128, 2013). "It is well known that the heart is involved in Duchenne muscular dystrophy (DMD) and Becker muscular dystrophy (BMD), both caused by mutations in the dystrophin gene on the short arm of the X-chromosome (Xp21)." (PMID 23870371, 2013). "The most common type, Duchenne muscular dystrophy (DMD), results from a loss of function of the dystrophin gene." (PMID 23185465, 2012). "As the commonly used mouse model to study Duchenne muscular dystrophy, this mouse carries the mutant dystrophin protein which leads to fiber necrosis, immune cell infiltration and defected regeneration." (PMID 22319554, 2012). "Duchenne muscular dystrophy (DMD) is one of the most common X-linked lethal diseases, and results from the mutation within the gene encoding dystrophin, a large cytoskeletal protein, whose ablation leads to membrane instability." (PMID 22348094, 2012). "The large deletion encompassing exons 18–44 of the DMD gene was detected in a patient with Duchenne Muscular Dystrophy by comparing the number of reads in these regions with other sequenced DNA samples." (PMID 22526018, 2012). "Indeed, in support of this, previous satellite cell/myoblast studies in dystrophin-deficient Duchenne muscular dystrophy (DMD) patients point to either elevated or decreased numbers of satellite cells in muscle, depending on the report and method used." (PMID 22887880, 2012). "However mutations in dystrophin, which cause the most common form of muscular dystrophy, Duchenne muscular dystrophy (DMD), also lead to loss of the sarcoglycans." (PMID 22640601, 2012). "Duchenne muscular dystrophy (DMD) is a severe form of muscular dystrophy with X-linked recessive inheritance, caused by mutations in the gene encoding dystrophin." (PMID 22238670, 2012). "Therapeutic strategies to replace defective dystrophin with utrophin in patients with Duchenne muscular dystrophy require full-characterization of both these proteins to assess their degree of structural and functional equivalence." (PMID 22911693, 2012). "Duchenne muscular dystrophy (DMD) and Becker muscular dystrophy (BMD) are both muscle wasting disorders caused by mutations in the DMD gene." (PMID 23259153, 2012). "Antisense therapy has recently been demonstrated with great potential for targeted exon skipping and restoration of dystrophin production in cultured muscle cells and in muscles of Duchenne Muscular Dystrophy (DMD) patients." (PMID 21611204, 2011). "Duchenne muscular dystrophy (DMD), caused by mutations in the dystrophin gene, is associated with severe cardiac complications including cardiomyopathy and cardiac arrhythmias." (PMID 21677768, 2011). "AONs are a promising therapeutic tool, as was recently shown by phase I and phase I/II clinical trials in Duchenne muscular dystrophy (DMD) boys carrying specific deletions in the DMD gene." (PMID 21909428, 2011). "In the most severe cases, such as Duchenne muscular dystrophy (DMD, caused by the lack of the dystrophin protein), muscle loss and fibrosis also cause premature death through respiratory and cardiac failure." (PMID 21798099, 2011). "Dystrophin is a large protein involved in the rare genetic disease Duchenne muscular dystrophy (DMD)." (PMID 21901138, 2011). "Utrophin is the autosomal homolog of dystrophin, the product of the Duchenne Muscular Dystrophy (DMD) locus." (PMID 22216264, 2011).
Duchenne muscular dystrophy (continued). "Despite the initial promise of myoblast transfer therapy to restore dystrophin in Duchenne muscular dystrophy patients, clinical efficacy has been limited, primarily by poor cell survival post-transplantation." (PMID 22195027, 2011). "PPARδ has also been implicated in the treatment of degenerative muscle diseases such as Duchenne muscular dystrophy (DMD), which is caused by the mutation of the dystrophin gene." (PMID 22040534, 2011). "Here we report the SB system is capable of stably integrating the ΔR4-R23/CTΔ micro-dystrophin gene into a conditionally immortal dystrophin deficient muscle cell-line, H2K SF1, a murine cell model for Duchenne muscular dystrophy." (PMID 22318674, 2011). "We identified SNP rs721699 in the Duchenne muscular dystrophy gene Dystrophin (DMD) [OMIM:300377] in the overall test and SNPs rs9887672, rs10218388 and rs5962575 in the IL-1 receptor accessory protein-like 2 (IL1RAPL2) gene [OMIM:300277] in the male test." (PMID 22050706, 2011). "Duchenne muscular dystrophy (DMD) is a prevalent neuromuscular disease resulting from a mutation affecting the dystrophin gene, and resulting in widespread deficiency of the muscle membrane protein, dystrophin." (PMID 22457847, 2011). "Duchenne muscular dystrophy (DMD) is a devastating X-linked muscle wasting disease, caused by mutations in the dystrophin gene." (PMID 22028826, 2011). "Microarray analyses of muscle from the dystrophin-deficient (mdx) mouse, an animal model of Duchenne muscular dystrophy (DMD), suggest that changes in miRNAs expression may contribute to the pathophysiology of muscular dystrophy." (PMID 20487562, 2010). "Duchenne Muscular Dystrophy (DMD) is a myopathy characterized by a defect in the p21 band of the X chromosome that is responsible for dystrophin, a protein located on the inner surface of the sarcolemma." (PMID 20492678, 2010). "Antisense-mediated exon skipping is one of the most promising approaches for the treatment of Duchenne muscular dystrophy and has recently been shown to correct the reading frame and restore dystrophin expression in vitro and in vivo." (PMID 21151513, 2010). "Duchenne muscular dystrophy (DMD) arises from some mutations of the human dystrophin gene." (PMID 19325525, 2009). "Antisense oligonucleotides (AOs) have been shown to induce dystrophin expression in muscles cells of patients with Duchenne Muscular Dystrophy (DMD) and in the mdx mouse, the murine model of DMD." (PMID 19351396, 2009). "Duchenne muscular dystrophy (DMD), a fatal disease caused by mutations in the gene encoding dystrophin, has been established as an excellent candidate for AO-based treatment." (PMID 19351396, 2009). "A number of these are transcription factors including the proinflammatory regulator NF-κB which has been shown to be activated in degenerating muscle of Duchenne muscular dystrophy patients and dystrophin-difficient mouse models." (PMID 19400950, 2009). "Duchenne muscular dystrophy (DMD) is a fatal x-linked disease caused by mutations in the gene encoding the 427 kDa membrane-associated cytoskeletal protein dystrophin, resulting in progressive body-wide muscle weakening and death usually in the early to mid third decade of life." (PMID 18384691, 2008). "This study was performed to examine the influence of dystrophin deficiency on fiber type composition of skeletal muscles in canine X-linked muscular dystrophy in Japan (CXMDJ), a large animal model for Duchenne muscular dystrophy." (PMID 18182116, 2008). "Duchenne muscular dystrophy (DMD) is caused by deficient expression of the cytoskeletal protein, dystrophin." (PMID 19649270, 2008). "Mental retardation (MR) is a clinical feature in a third of patients suffering from Duchenne muscular dystrophy (DMD), an X-linked genetic disease caused by mutations in the dystrophin gene." (PMID 19649270, 2008).
Duchenne muscular dystrophy (continued). "In Duchenne muscular dystrophy (DMD), nonsense or deletion mutations in the dystrophin gene disrupt translation of a functional dystrophin protein." (PMID 17604456, 2007). "The situation is reminiscent of the high frequency of deletions within the dystrophin gene found in patients with Duchenne Muscular Dystrophy." (PMID 17277737, 2007). "Duchenne muscular dystrophy (DMD), caused by mutations in the dystrophin gene, is lethal." (PMID 16011810, 2005). "The second was a study of the mdx mouse, an animal model of Duchenne muscular dystrophy, with a premature stop codon in exon 23 of dystrophin (MDX dataset)." (PMID 16103915, 2005). "Duchenne muscular dystrophy is a genetic disorder that causes the absence of Dystrophin, usually due to mutations in the DMD gene, which presents unique challenges for diagnosis." (PMID 40332074, 2025). "Duchenne muscular dystrophy is a monogenic X-linked genetic disorder that is caused due to the absence of dystrophin." (PMID 41164778, 2025). "Notably, even modest editing levels were effective in some disease models; for example, ~ 5–6% dystrophin restoration in Duchenne muscular dystrophy was sufficient to produce functional benefit." (PMID 40465697, 2025). "In this context, it has been reported that miRNA-31 negatively regulates dystrophin gene expression, and interfering with its activity could help improve dystrophin recovery in Duchenne muscular dystrophy patients, increasing skeletal muscle regeneration." (PMID 40016564, 2025). "Duchenne muscular dystrophy (DMD) manifests as a hereditary condition that diminishes muscular strength through the progressive degeneration of structural muscle tissue, which is brought about by deficiencies in the dystrophin protein required for the integrity of muscle cells." (PMID 40649811, 2025). "Duchenne muscular dystrophy (DMD) is an X-linked recessive disorder caused bymutations or deletions in the Dystrophin gene resulting in an absent ornonfunctional protein." (PMID 40160579, 2025). "They explore how dystrophin isoforms interact with other proteins, and consider how understanding these interactions could help in treating neurological complications in Duchenne muscular dystrophy." (PMID 39673425, 2025). "For example, a Duchenne muscular dystrophy (DMD) patient treated with a high-dose AAV-packaged CRISPR transgene to restore dystrophin (the faulty DMD gene) expression led to an immune response and rapid death, possibly arising from a high level of accumulated vector genome." (PMID 41394966, 2025). "Duchenne muscular dystrophy (DMD) is a severe muscle disorder caused by absence of dystrophin, a protein that anchors the contractile elements of the muscle fiber to the extracellular matrix, which results in progressive muscle degeneration." (PMID 39982358, 2025). "Duchenne muscular dystrophy (DMD) is a severe X-linked neuromuscular disorder caused by the absence of dystrophin, leading to progressive muscle degeneration, including cardiac damage and impaired innervation." (PMID 40724839, 2025). "Among the splicing‐correcting ASOs, US FDA has approved mRNA eteplirsen, golodirsen, viltolarsen, and casimersen, which promote exon skipping in the DMD gene, enabling the production of a partially functional dystrophin protein in patients with Duchenne muscular dystrophy." (PMID 40425033, 2025). "Similarly, eteplirsen (2016) induces DMD exon 51 skipping to regenerate functional dystrophin and slow disease progression in Duchenne muscular dystrophy." (PMID 41399527, 2025). "In the primary report of a phase 1b trial, adeno-associated virus gene therapy with fordadistrogene movaparvovec in patients with Duchenne muscular dystrophy was well tolerated in an ambulatory cohort, and mini-dystrophin expression was increased in the high-dose cohort." (PMID 40579547, 2025).